MTOR (mechanistic target of rapamycin kinase)
Diseases named in the same sentence as MTOR in open-access papers (continued):
Sharing a sentence is not in itself a finding about the gene and the disease.
ovarian carcinoma (continued). "However, phase II trials of temsirolimus, a single agent mTOR inhibitor, have shown little activity in patients with persistent or recurrent ovarian cancer." (PMID 33659215, 2020). "The activation of AKT and mTOR was also induced in hypoxic primary ovarian cancer cells." (PMID 32312328, 2020). "Therefore, the identification of novel agents that target and intervene with NF-κB and mTOR signaling should aid in effective treatment of ovarian cancer and improvement of clinical outcomes." (PMID 33234722, 2020). "Accordingly, we focused on whether cardamonin induces apoptosis in ovarian cancer through effects on the mTOR and NF-κB pathways." (PMID 33234722, 2020). "In this study, we evaluated the synergistic effects of neoadjuvant metformin combined with chemotherapy in ovarian cancer via the AKT/mTOR pathway both in vitro and in vivo and found that poor glucose control diminished the synergistic, antitumor effects of combination treatment." (PMID 32825834, 2020). "Thus, the overexpression of PBK activated ovarian cancer cell autophagy through suppressing the mTOR signaling pathway." (PMID 30778048, 2019). "To ascertain whether the Akt/mTOR pathway has an important role in Pae-induced autophagy, we investigated key proteins related to the Akt/mTOR pathway in Pae-treated ovarian cancer cells by western blot analysis." (PMID 31406198, 2019). "Preclinical models and early clinical data have suggested that PIK3CA and PTEN mutations may predict sensitivity to treatment with PI3K/AKT/mTOR inhibitors, such as everolimus, in multiple tumor types, including high-grade epithelial ovarian cancer." (PMID 31197119, 2019). "In addition, the mTOR survival pathway was activated in lung and ovarian cancer cell lines that were treated with cisplatin, and sensitivity to cisplatin was enhanced by inhibiting the mTOR pathway." (PMID 30842342, 2019). "Here, we verified for the first time that PBK could promote ovarian cancer cell autophagic flux through activating the mTOR pathway." (PMID 30778048, 2019). "Plakophilin 3 in ovarian cancer tissue modulates autophagy through the JNK/ERK/mTOR pathways." (PMID 31358050, 2019). "Preclinical studies on ovarian tissue samples of ovarian cancer patients showed that the mTOR pathway is upregulated, indicating that rapalogs may be a useful therapeutic option." (PMID 31569540, 2019). "Furthermore, mTOR inhibition resulted in GDH inhibition leading to reduced glutamine-induced proliferation in ovarian cancer cells." (PMID 30728400, 2019). "In addition, the combination of rapamycin (an mTOR inhibitor) and Pae in ovarian cancer cells also showed similar results." (PMID 31406198, 2019). "Likewise, the phosphoinositide 3-kinase (PI3K)/protein kinase B (AKT)/mammalian target of rapamycin (mTOR) pathway is also a central regulator of the ovarian cancer." (PMID 29401696, 2018). "It has become clear that there is a role for inhibition of mTOR in ovarian cancer therapy." (PMID 30237852, 2018). "As SOC are known to interact with the frequently deregulated PI3K/Akt/mTOR pathway, they could offer a relevant target to overcome apoptosis resistance in ovarian carcinoma." (PMID 30338034, 2018). "In addition, this review suggests a connection between the PIM kinases and the PI3K/AKT/mTOR pathway and their parallel mechanism in the regulation of ovarian cancer." (PMID 29401696, 2018). "Furthermore, LSD1 is a potential regulator of ovarian cancer cell progression and regulates autophagy via the mTOR signaling pathway in ovarian cancer cells." (PMID 30497519, 2018). "However, also in this context literature data are controversial, being over-expression of miR-100 either responsible of decreased or increased sensitivity to mTOR inhibitors, in lymphoblastoid or ovarian cancer, respectively." (PMID 29938004, 2018).
ovarian carcinoma (continued). "Based on our data, however, we hypothesize that a diet that is high in casein might increase the growth of ovarian cancer cells are naturally present in mice through the activation of the IGF/Akt/mTOR pathway." (PMID 29844867, 2018). "Taken together, these results indicate that EpCAM and PI3K/Akt/mTOR targeted therapy might be promising strategies for overcoming chemoresistance in patients with ovarian cancer." (PMID 28574829, 2017). "Indeed, mTOR inhibitors are being tested in various stages of clinical development for ovarian cancer." (PMID 28938571, 2017). "Lau and Leung59 have identified that PI3K/Akt/mTOR is required for insulin-like growth factor 1-induced E-cadherin down-regulation and up-regulation of E-cadherin transcriptional repressors, Snail and Slug, in human ovarian cancer cells." (PMID 28900284, 2017). "Interestingly, our previous studies of breast and ovarian cancer cells showed that pharmacological inhibition of PI3K/mTOR results in the specific apoptosis of matrix-detached tumour cells, whereas ECM-attached cells remain viable." (PMID 28071763, 2017). "Similarly, a study in a large panel of ovarian cancer cell lines identified a link between K‐Ras/BRAF mutation status and resistance to the dual PI3K/mTOR inhibitor, PF‐04691502." (PMID 28544747, 2017). "mTOR signaling is frequently hyper-activated in ovarian cancer." (PMID 28938571, 2017). "Combining PI3K/AKT/mTOR and PARP inhibitors could recapitulate the synthetic lethality observed in ovarian cancer patients with BRCA germ line mutation treated with olaparib." (PMID 28286604, 2017). "Further, the induction effects of mTOR inhibitor, rapamycin on cell cycle G1 phase arrest in ovarian cancer cells was impaired by AE2 overexpression, which suggested AE2 might promote cell cycle progression partially by activating mTOR/p70S6K1 pathway." (PMID 28743911, 2017). "Aberrant activation of mTOR contributes to ovarian cancer progression." (PMID 28938571, 2017). "Given that the PI3K/AKT/mTOR pathway is frequently activated in ovarian cancer and obesity, this study aimed to access the anti-tumorigenic efficacy of everolimus in ovarian cancer cells under different glucose conditions in vitro and in lean and obese mouse models of serous ovarian cancer in vivo." (PMID 26959121, 2016). "Therefore, our illustration demonstrated that cRGD inhibited VM formation in ovarian cancer via not only down-regulating uPA expression which reduced MMP-2 efficiency to cleave Laminin5γ2 through AKT/mTOR/MMP-2/Laminin5γ2 signal pathway but also reducing EMT." (PMID 26992227, 2016). "Both synthetic and natural mTOR inhibitors can be used for the treatment of ovarian cancers." (PMID 27886120, 2016). "Given that obesity-induced tumor growth involves alterations in AKT/mTOR signaling, everolimus may be a logical choice in obese ovarian cancer patients." (PMID 26959121, 2016). "Our finding that pharmacologic inhibition of the mTOR pathway decreased the rate of formation of TNTs between ovarian cancer cells may provide a rationale for a new approach to preventing development of chemotherapy resistance via a TNT-mediated mechanism." (PMID 27223082, 2016). "Thus, consistent with its inhibitory effect on cell proliferation, the PI3K inhibitor BKM120 treatment resulted in attenuated PI3K/AKT/mTOR signaling in PIK3CA mutant ovarian cancer cells." (PMID 26909613, 2016). "Given that the mTOR pathway is highly activated with increased severity of obesity in humans, everolimus may be more successful when used in obese patients with ovarian cancer by reducing mTOR activity." (PMID 26959121, 2016).
ovarian carcinoma (continued). "Preclinical and clinical studies in patients with breast, cervical, endometrial, and ovarian cancer treated with PI3K/AKT/mTOR inhibitors could demonstrate a higher response rate in patients with activating PIK3CA mutation than patients without mutation." (PMID 26943575, 2016). "We therefore tested the hypothesis that combined inhibition of both IKKβ and PI3K/mTOR pathways may inhibit proliferation and survival of ovarian cancer cells more effectively than individual inhibition." (PMID 26657155, 2016). "Furthermore, Bahrami and colleagues indicated that monepantel induced autophagy in human ovarian cancer cells through disruption of the mTOR/p70S6K signalling pathway." (PMID 27825125, 2016). "Therefore, Notch3 expression and pS6 expression play important roles in PI3K/AKT/mTOR signaling and ovarian epithelial cancer development." (PMID 27445438, 2016). "The mTOR pathway is a central regulator of various oncogenic processes that contribute to cell proliferation, cell cycle progression, metabolism, angiogenesis and drug resistance in a wide variety of cancers including ovarian cancer." (PMID 26959121, 2016). "Also in an ovarian cancer cell line as well as in xenograft models impeded mTOR pathway activity increases the efficacy of paclitaxel." (PMID 27090655, 2016). "In addition to the apoptosis markers, we also investigated the expression of mTOR signaling pathways since it is frequently detected in ovarian cancers." (PMID 28066412, 2016). "In addition, studies have also shown that the activation of the PI3K/AKT/mTOR signal pathway contributes to the platinum-based resistance and poor prognoses in ovarian cancer." (PMID 26325371, 2015). "Activation of the MAPK and phosphatidylinositol 3 kinase/Akt/mTOR pathways plays a crucial role in the control of cell growth and survival in ovarian cancer, and inhibition of these pathways leads to the inhibition of ovarian cancer growth." (PMID 26045471, 2015). "Furthermore, spearman's rank correlation analysis revealed an inverse correlation between miR-497 and mTOR, and p70S6K1 exists in our ovarian cancer samples." (PMID 26238185, 2015). "Interestingly, forced expression of mTOR and p70S6K1 partially or completely restored miR-497-inhibited cisplatin resistance in ovarian cancer cells." (PMID 26238185, 2015). "In addition, significant attenuation of capillary formation was also evident from the metformin-treated group, consistent with a previous report proposing an AMPK/mTOR-dependent antiangiogenic effect of metformin on ovarian cancer." (PMID 25883966, 2015). "Ovarian cancer cells show a dysregulation of PI-3 K/Akt/mTOR pathway." (PMID 26141064, 2015). "Moreover, potential connections between calcium signaling and PI3K/AKT/mTOR pathway have been reported in a number of cell types included ovarian cancer." (PMID 25627260, 2015). "Targeting mTOR may overcome cisplatin resistance in ovarian cancer patients and an early response to everolimus treatment was seen in an animal model of cisplatin-resistant ovarian cancer." (PMID 25061503, 2014). "Mutations in KRAS and BRAF, which may activate the mTOR/PI3K/AKT pathway, are common in low-grade ovarian cancers (60 %) but rare in high-grade cancers." (PMID 24848881, 2014). "Furthermore, attachment of cells to lrECM was shown to protect cells from apoptosis in ovarian cancer 3D cultures upon exposure to the PI3K/the mammalian target of rapamycin (mTOR) inhibitor, BEZ235." (PMID 24887773, 2014). "Indeed, activation of mTOR is almost ubiquitous in ovarian carcinoma lesions and often correlates with poor prognosis." (PMID 25193855, 2014). "The study concludes that miR-199a is able to reverse cisplatin resistance in human ovarian cancer cells through the inhibition of mTOR and that mTOR may be the target of miR-199a during this process." (PMID 24137412, 2013).
ovarian carcinoma (continued). "In addition, our studies suggest that FGF2 exerts its effects in human ovarian cancer cells via the activation of the PI3K/Akt/mTOR and MAPK/ERK signaling pathways and the subsequent increased expression of Slug and ZEB1." (PMID 23554977, 2013). "Other studies have reported that the mTOR pathway is activated in ovarian cancer cells." (PMID 23819061, 2013). "Based on the present data, we attempted to identify whether mTOR is the target gene of miR-199a, which may explain miR-199a-related cisplatin resistance in ovarian cancer cells." (PMID 24137412, 2013). "The mTOR signaling pathway may be involved in regulating the phosphorylation status of p70S6K at Ser371 in the mediation of chemoresistance in ovarian cancer." (PMID 24137412, 2013). "The purpose of the present study was to define the role of this miRNA during the development of cisplatin drug resistance in the human OV2008 and C13* ovarian cancer cell lines by analyzing the expression levels of miR-199a and mTOR, a possible target of miR-199a." (PMID 24137412, 2013). "Knocking down mTOR by shRNA decreased paclitaxel-induced Akt phosphorylation at Ser473 but not at Thr308 and it also caused CaOV3 ovarian cancer cells to become more sensitive to paclitaxel." (PMID 24042258, 2013). "Targeting mTOR directly can also decrease ovarian cancer cell proliferation and migration." (PMID 23591839, 2013). "A recent study has shown that PI3K/AKT/mTOR signaling is involved in EOC development and resistance to cisplatin, since downregulation of AKT with triciribine or shRNA transfection of ovarian cancer cells decreased their resistance to cisplatin via mTOR/survivin signaling." (PMID 22481932, 2012). "Phase I–II trials are currently evaluating mTOR inhibitors in ovarian cancer patients." (PMID 23155381, 2012). "Up to date, there is only preclinical data available to suggest that mTOR inhibition might be beneficial in epithelial ovarian cancer." (PMID 19240722, 2009). "Ovarian cancer tumorigenesis may be due to dysregulations in the PI3K/Akt/mTOR signaling pathway." (PMID 41608512, 2026). "AuNPs inhibit ovarian carcinoma invasiveness by targeting key oncogenic pathways: impeding MAPK signaling, suppressing EMT-associated proteins, and disrupting the IGFBP2/mTOR/PTEN autoregulatory axis, downregulating IGFBP2, suppressing PI3K/AKT/mTOR activation, and reactivating PTEN." (PMID 41018109, 2025). "Furthermore, sEVs from human umbilical cord mesenchymal stem cells (MSCs) can regulate the expression of nucleus accumbens-associated protein 1 (NACC1) by transporting miR-18a-5p, which influences the Akt/mTOR pathway, thereby curbing ovarian cancer cell proliferation." (PMID 40008006, 2025). "Similarly, the mTOR inhibitor INK128 re-sensitized ovarian cancer cells to carboplatin-induced DNA damage by disrupting the selective translation of mRNAs involved in DNA repair and cell survival, highlighting the critical role of mTOR signaling in mediating resistance to DNA damage-based therapies." (PMID 40429728, 2025). "Additionally, a study on ovarian cancer showed that fucoxanthin could inhibit the proliferation, migration, and invasion of ovarian cancer A2780 cells through the Akt/mTOR pathway." (PMID 39125009, 2024). "Therefore, we concluded that ITGB2 could promote the invasion ability of ovarian cancer cells via the PI3K/AKT/mTOR pathway." (PMID 38345576, 2024). "As a result of ARHI re-expression in ovarian cancers, there was inhibition of the PI3K/AKT/mTOR pathway, which led to Atg4 upregulation and its colocalization with cleaved microtubule-associated protein light chain 3 (LC3) in autophagosomes, allowing ovarian cancer cells to remain dormant." (PMID 38994941, 2024). "Therefore, we suggest that NC could trigger autophagy and apoptosis of ovarian cancer cells through Akt/mTOR signaling pathway, and NC may potentially be a target for chemotherapy against ovarian cancer." (PMID 37317923, 2023).
ovarian carcinoma (continued). "The upregulation of mammalian target of rapamycin (mTOR), a master regulator of translation initiation, results in the increased expression of cancer-promoting genes such as eIF4E, a limiting factor for translation initiation in most cancers, including ovarian cancer." (PMID 37842240, 2023). "By targeting the PI3K/Akt/mTOR pathway in tandem, these compounds may exhibit a synergistic inhibition, effectively amplifying their anti-cancer prowess and offering a novel treatment modality against ovarian cancer." (PMID 38239204, 2023). "Inhibition of mTOR could inhibit the cell proliferation and migration in ovarian cancer." (PMID 37304865, 2023). "Additionally, we identified a novel mechanism by which NANOG increases the metastatic potential of ovarian cancer cells by regulating the AMPK/mTOR pathway, which might foster new therapeutic strategies for the treatment of ovarian cancer." (PMID 36114703, 2022). "Similarly, macranthoside B, a saponin compound from Lonicera macranthoides, could induce cell death and enhances autophagy in ovarian cancer through the AMPK/mTOR pathway by a mechanism thought to involve the accumulation of reactive oxygen species." (PMID 35052471, 2022). "Thus, RAD21 promoted ovarian cancer progression by activating the Akt/mTOR signaling pathway." (PMID 35860572, 2022). "Therefore, dezocine may exert anti-cancer activity by inhibiting activation of the Akt/mTOR signaling pathway in ovarian cancer." (PMID 36568517, 2022). "In addition to participating in basic functions related to mitochondrial oxidative phosphorylation, high expression of MRPL15 in ovarian cancer may be related to cell cycle, DNA repair, DNA replication, and the mTOR signaling pathway." (PMID 33934540, 2021). "Moreover, by producing PGE2, MDSCs increase the PD-L1 expression in ovarian cancer cells by activating AKT/mTOR signaling, which may facilitate ovarian cancer cells to escape destruction by the immune system." (PMID 33562495, 2021). "We speculated that TTK inhibition decreases autophagy through the mTOR pathway in ovarian cancer." (PMID 34876569, 2021). "Therefore, MRPL15 may lead to immune tolerance of ovarian cancer by participating in the downstream mTOR pathway of IDO1, thereby promoting the progression of ovarian cancer." (PMID 33934540, 2021). "Thus, we speculated that SRT2183 induced the autophagy by inhibiting the activity of p-mTOR in ovarian cancer cells." (PMID 33223507, 2020). "Thus, dual inhibition of PI3K and mTOR has the advantage to overcome the upregulation of PI3K due to the feedback loop caused by mTOR inhibition, which may improve treatment response for ovarian cancer." (PMID 33659215, 2020). "Furthermore, the mammalian target of rapamycin (mTOR) pathway is overactivated in approximately 70% of ovarian cancers and regulates protein translation of cell growth regulators such as cyclin D1, hypoxia inducible factor 1α (HIF1α) and MYC, all essential for survival under cellular stress." (PMID 32146550, 2020). "The effects of low-concentration metformin on AKT/mTOR signaling in ovarian cancer remain unclear." (PMID 32825834, 2020). "However, Phase II trials in ovarian cancer, including resistant cases, have demonstrated a diverse range of responses to mTOR inhibitors, such as temsirolimus, indicating that better criteria are necessary to determine which patients are the best candidates for mTOR inhibitors." (PMID 30866519, 2019). "However, mTOR signaling could partially explain the enhanced aggressiveness of ovarian cancer cells." (PMID 31372520, 2019). "In addition, DHA suppressed mTOR and induced autophagy in cisplatin-resistant ovarian cancer cells." (PMID 31762815, 2019). "Therefore, the Akt/mTOR signalling pathway may be partly involved in autophagy activated by Pae in ovarian cancer cells." (PMID 31406198, 2019).